PTX3 (pentraxin 3)
Diseases named in the same sentence as PTX3 in open-access papers (continued):
Sharing a sentence is not in itself a finding about the gene and the disease.
acute coronary syndrome (22 papers, 2012 to 2025). Signs and symptoms related to acute ischemia of the myocardium secondary to coronary artery disease. "Importantly, in patients with acute coronary syndrome, elevated Ptx-3 levels were associated with a higher rate of mortality, even in long-term observational studies." (PMID 32085400, 2020). "Indeed, increased Ptx-3 levels are associated with CAD including acute coronary syndrome." (PMID 32085400, 2020). "Increased plasma PTX3 levels were reported in patients with carotid stenosis and acute coronary syndrome, and PTX3 is also a candidate biomarker for plaque vulnerability." (PMID 34680994, 2021). "Recently, many clinical studies have demonstrated that plasma PTX3 concentrations rapidly increase in patients with the acute coronary syndrome (ACS)." (PMID 31147578, 2019). "Accordingly, PTX3 levels are significantly increased in patients with carotid stenosis, as well as in patients with acute coronary syndrome, in whom PTX3 is a candidate biomarker for plaque vulnerability." (PMID 27559355, 2016). "Plasma PTX3 was accordingly reported to be elevated in patients with arterial stiffness and subclinical or unstable atherosclerotic lesions, and high circulating PTX3 is observed in acute coronary syndromes (ACS)." (PMID 24215445, 2013). "In both acute infections and acute coronary syndromes, the role of PTX3 appears to be primarily protective in that the long pentraxin dampens the inappropriate, exaggerated inflammatory response." (PMID 22577258, 2012). "In the field of cardiovascular diseases, increased serum PTX3 levels have been reported in patients with acute coronary syndromes." (PMID 23029266, 2012). "Although pentraxin-3 levels were generally higher in the S-CCS group, the variation was modest and nonsignificant, aligning with meta-analyses that report stronger associations of pentraxin-3 with acute coronary syndromes rather than stable CAD." (PMID 40430046, 2025). "Pentraxin 3 (PTX3) levels were also found to be elevated in cases of acute coronary syndrome." (PMID 40725061, 2025). "For example, PTX3 has been observed in atherosclerotic plaques, and there are theories suggesting that systemic PTX3 levels might be a useful indicator of acute coronary syndrome, because of its reflection of vascular inflammation." (PMID 28225768, 2017). "Subgroup analyses showed that the associations between PTX-3 and poor prognosis in CAD were consistent in patients with ST-segment elevation myocardial infraction, non-ST-segment elevation acute coronary syndrome, and stable CAD (p < 0.05 for each subgroup)." (PMID 35083296, 2022). "Long pentraxin 3 (PTX3) is a component of the pentraxin superfamily and a potential marker of vascular damage and inflammation, associated with negative outcome in patients with acute coronary syndromes (ACS)." (PMID 24215445, 2013).
glioblastoma (22 papers, 2018 to 2025). The most malignant astrocytic tumor (WHO grade IV). "Further evidence supports the role of PTX3 in regulating the proliferation and migration of tumor-associated macrophages and dendritic cells in glioblastoma." (PMID 39594709, 2024). "Current studies show that overexpression of PTX3 in glioblastoma cells is associated with increased invasion and the IL8–VEGF signaling axis." (PMID 37091145, 2023). "Another study on glioblastoma demonstrated that PTX3 modulates the activity of tumor-infiltrating macrophages." (PMID 39594709, 2024). "In cases of recurrent glioblastoma, PTX3 gene expression was found to be lower in the recurrent tumors than in primary tumors, indicating a possible dynamic interaction between PTX3 expression and the tumor microenvironment during tumor progression." (PMID 39594709, 2024). "PTX3 is a promoter of cell invasiveness and is involved in the progression of various cancers, including glioblastoma, where it correlates with the disease grade, thanks to its downstream target genes involved in migration and invasion." (PMID 36009036, 2022). "On the other hand, PTX-3 acts like a double-edge sword even in case of glioblastomas, as it promotes CD80 activation and Th1 differentiation." (PMID 36499628, 2022). "Conversely, the increase in PTX3 is correlated to glioblastoma, with an increase in IL-8 and VEGF, two important factors in angiogenesis." (PMID 36555812, 2022). "It has been reported that hypoxia regulates the expression of pro-inflammatory genes like COX-2, NOS2, PTX3 in glioblastoma cancer stem cells." (PMID 29719610, 2018). "Notably, glioblastomas (GBMs) display markedly higher PTX3 levels than low-grade astrocytomas or oligodendrogliomas." (PMID 41515435, 2025). "Variations in PTX3 expression within glioblastomas may occur between the tumor core and the infiltrative border." (PMID 40656950, 2025). "The results showed that elevated PTX3 expression was associated with reduced survival rates in patients with G3, G4, IDH wild-type, 1p/19q alterations, as well as in both female and male patients diagnosed with astrocytoma or glioblastoma." (PMID 40656950, 2025). "In glioblastoma, PTX3 has been reported as promoting tumor progression by inhibiting autophagy." (PMID 39594709, 2024). "Therefore, we validated by qRT-PCRs the expression of both ADAM12 and PTX3 in siADAR2 glioblastoma cells (A172 and U87MG)." (PMID 36009036, 2022). "This work reveals novel mechanism of pentraxin 3 mediated glioblastoma progression." (PMID 32984316, 2020). "in 2021 found that the prognosis of glioblastoma (GBM) can be determined by seven differentially expressed genes (DEGs) 47, namely CLEC5A, HOXC6, HOXA5, CCL2, GPRASP1, BSCL2, and PTX3." (PMID 39132508, 2024). "The enhanced expression of PTX3 correlates with the IL8-VEGF signaling axis and increases the invasion in glioblastoma cells whereas serum PTX3, IL-8, and VEGF levels decreased in gastric carcinoma." (PMID 36555812, 2022). "Our study shows the cells grown in 3D-GMH with serum overexpress and secrete CXCL1, CXCL5, IGFBP2, PTX3, THBS1, VEGFA, and VCAM1—all genes expressed in perivascular or perinecrotic zone of glioblastoma tissues that are hotspots for immune cells." (PMID 34489494, 2021). "Similarly, interactions between PTX3 and inflammatory pathways, including the IL-17 and tumor necrosis factor (TNF) pathways, were identified in a glioblastoma study." (PMID 39594709, 2024). "In this study, pentraxin 3 is recognized as prognostic prediction biomarker of glioblastoma and can promote glioblastoma progression through negative modulating tumor cells autophagy." (PMID 32984316, 2020). "We used data from the GEO and TCGA databases and identified five genes (ITGA5, MMP9, PTPRN, PTX3, and STX1A) that could affect the survival rate of glioblastoma patients and that were differentially expressed between glioblastoma patients and non-tumors groups." (PMID 33767729, 2021).
Insulin resistance (22 papers, 2012 to 2025). Increased resistance towards insulin, that is, diminished effectiveness of insulin in reducing blood glucose levels. "Nevertheless, it should be noted that our study is the first assessed complex association between PTX3 levels and nutritional status, insulin resistance, hormone levels, and systemic microinflammation in young PCOS and non-PCOS women." (PMID 32934654, 2020). "Further, PTX3 was positively correlated with insulin sensitivity and negatively correlated with insulin resistance, although these associations were modest." (PMID 26842615, 2016). "For example, in a study of GDM patients, some inflammatory factors and oxidative stress indicators in serum were found to be associated with insulin resistance, such as increased levels of serum pentraxin-3 (PTX3) and high-sensitivity C-reactive protein (hs-CRP) in GDM patients." (PMID 41488068, 2025). "Indices of glucose metabolism calculated from the OGTT at 30–32 weeks revealed that PTX3 levels was positively associated with insulin sensitivity (r = 0.23, p < 0.001) and β-cell function (r = 0.18, p = 0.003), and negatively with insulin resistance (r = −0.23, p < 0.001)." (PMID 26842615, 2016). "Furthermore, recent studies investigating the association between plasma PTX3 levels and insulin resistance in lean, overweight, and obese individuals supports our data of a negative correlation with glucose intolerance." (PMID 26842615, 2016). "Additionally, PTX-3, an acute-phase protein, rises in response to inflammatory stimuli from visceral fat and is closely linked to immune and inflammatory processes that contribute to insulin resistance." (PMID 40153192, 2025). "Another study reported that children with migraine showed significantly higher levels of pentraxin-3 (PTX-3), insulin, and insulin resistance, suggesting a role for inflammation and vascular endothelial dysfunction in pediatric migraine." (PMID 40149800, 2025). "Anthropometric parameters, insulin resistance indices, lipid profiles, and inflammatory markers including high sensitivity C-reactive protein (hsCRP), pentraxin 3 (PTX3), adiponectin, and chemerin were measured." (PMID 22509348, 2012). "However, in the subgroup analysis based on insulin resistance status, follicular fluid PTX-3 levels were significantly higher in IR + PCOS patients." (PMID 41013753, 2025). "Therefore, the positive effect of a decrease in body weight on lipid profile and insulin resistance through regular exercise supports the positive increase in PTX3 level in this study." (PMID 39372725, 2024). "Moreover, there are studies suggesting a correlation between increased PTX3 concentration in patients and insulin resistance in patients with PCO syndrome." (PMID 36290747, 2022). "However, the results of studies assessed circulating PTX3 levels in PCOS women are inconsistent, and its associations with nutritional status and insulin resistance are unclear." (PMID 32934654, 2020). "PTX3 was positively correlated with hs-CRP, body mass index (BMI), fasting plasma glucose (FPG), and homeostasis model assessment of insulin resistance (HOMAIR)." (PMID 31721795, 2019). "This study showed that the positive effects of PTX3 on the lipid profile are independent of insulin resistance." (PMID 39372725, 2024). "Serum PTX-3 level and the TyG index of the NAFLD patients were significantly higher than those of the healthy controls (P < 0.001), which was closely related with the BMI, ALT, and insulin resistance." (PMID 35059041, 2021). "Our results show that the decrease in PTX3 levels observed in obese women is distorted in PCOS by microinflammation, and possibly, dysfunction of stroma adipose tissue and liver steatosis is reflected by enhanced insulin resistance." (PMID 32934654, 2020).
Insulin resistance (continued). "Our results show that the decrease in PTX3 levels observed in obese is distorted in PCOS by microinflammation, and possibly, dysfunction of stroma adipose tissue and liver steatosis is reflected by enhanced insulin resistance." (PMID 32934654, 2020). "However, consensus has not yet been reached; a study report that plasma PTX3 levels in women with PCOS is reduced, whereas yet another study shows PTX3 levels to be elevated in PCOS and positively correlated with insulin resistance." (PMID 25158044, 2014). "PTX-3 may serve as a potential biomarker of ovarian inflammation and compromised oocyte competence, independent of BMI or systemic insulin resistance." (PMID 41013753, 2025). "PTX3 was positively correlated with hs-CRP, body mass index, fasting blood glucose, and HOMA-IR, suggesting that inflammation and oxidative stress may be involved in the development of insulin resistance in GDM." (PMID 41488068, 2025). "The negative correlation between anthropometric measurements and PTX3 revealed in non-POCS suggests that adipose tissue is not a major source of PTX3, and that insulin resistance inhibits its production, and the severity of inflammation is too small to induce PTX3 expression not only in adipocytes." (PMID 32934654, 2020).
vasculitis (22 papers, 2008 to 2026). "PTX3, which is a marker of atherosclerosis or local vasculitis in SLE, is secreted by dendritic cells and ECs in response to inflammation." (PMID 37893187, 2023). "A recent study showed that anti-PTX3 antibodies correlated with the Birmingham Vasculitis Activity Score (BVAS) at baseline, and plasma and urinary PTX3 levels are increased in active AAV disease, especially in patients with renal involvement." (PMID 36911748, 2023). "In contrast to CRP, PTX3 is produced at the site of inflammation, and high levels have been found in various forms of vasculitis and in atherosclerotic abdominal aorta." (PMID 36606286, 2022). "Although PTX3 represents a novel acute‐phase reactant produced at sites of active vasculitis and correlates with disease activity, the vasopathology of SAO is completely different from that of vasculitis." (PMID 33210471, 2021). "Elevated PTX-3 levels correlated to elevated neutrophil counts, a known source of PTX-3 in acute inflammation and an important player in the development of KD vasculitis." (PMID 32670996, 2020). "PTX3, an acute-phase reactant produced at sites of active vasculitis, is an indicator of active small vessel vasculitis." (PMID 29850627, 2018). "Several recent studies have shown that there is extensive local production of PTX3 in inflammatory vascular lesions, such as atherosclerotic plaques and vasculitis." (PMID 24060373, 2013). "Molecule pentraxin 3 (PTX3), which is associated with complement activation in the alternative pathway and vasculitis, may also be a biomarker." (PMID 37893187, 2023). "Similar levels of pentraxin-3 were observed between active and inactive vasculitis." (PMID 36292253, 2022). "PTX3 levels that were evaluated in vessels were not only reported to be involved in rheumatological diseases such as systemic lupus erythematosus and rheumatoid arthritis, but also in vasculitis such as small vessel vasculitis and giant cell arteritis." (PMID 33529185, 2021). "Moreover, in longitudinal analysis, anti-PTX3 antibodies reactivity decreased significantly after remission, suggesting a possible involvement of these antibodies in the vasculitis pathophysiology, together with other ANCA antibodies." (PMID 32734361, 2020). "Furthermore, in vasculitis PTX3 has been suggested a possible biomarker for disease activity." (PMID 24060373, 2013). "Biomarkers such as soluble thrombomodulin and pentraxin 3 are indicative of vascular endothelial damage, and their levels rise in systemic vascular disorders like DIC and vasculitis." (PMID 38255886, 2024). "Thus, anti-PTX3, like MPO and PR3 ANCA, may participate to vasculitis pathophysiology, favouring primed neutrophil degranulation and/or clearance of apoptotic neutrophil in an immunogenic context." (PMID 26797217, 2016). "However, the PTX3 levels were mainly affected by active vasculitis, but not the prednisolone dose." (PMID 33529185, 2021). "We also did not observe anti-PTX3 aAbs in GCA patients, suggesting that anti-PTX3 aAbs may be limited to some vasculitis subtypes." (PMID 26797217, 2016).
periodontitis (21 papers, 2012 to 2025). An acute or chronic inflammatory process that affects the tissues that surround and support the teeth. "Recently, severe periodontitis was linked with vascular systemic inflammation in patients with chronic migraine via increased levels of acute-phase reactant PTX3 and sTWEAK." (PMID 33671172, 2021). "In the present animal study, experimental periodontitis was associated with increased serum levels of systemic inflammatory biomarkers such as IL-6, PTX3, and sTWEAK during 21 days of experiment." (PMID 31583485, 2020). "Recently, periodontitis was found to be associated with high levels of IL-6, PTX3, and sTWEAK in patients with cerebral small vessel disease increasing almost 3 times the likelihood of having this type of AVD." (PMID 31583485, 2020). "Contrasting evidence, however, suggest osteoclastogenesis-promoting effects of PTX3, where its expression has been associated with periodontitis, arthritis, and bone metastasis, conditions hallmarked by inflammation and bone resorption." (PMID 31787987, 2019). "Other authors have investigated the role of PTX3 in chronic inflammatory diseases with aggravated bone resorption, including periodontitis, arthritis, and tumor-associated inflammation, showing increased PTX3 levels, especially in areas of inflammation." (PMID 29556234, 2018). "A study examined the level of IL-Iβ and PTX3 associated with stages of periodontitis." (PMID 35270581, 2022). "Similarly, systemic elevated levels of PTX3 and soluble fragment of tumor necrosis factor-like weak inducer of apoptosis (sTWEAK) were linked with periodontitis patients." (PMID 33671172, 2021). "Further studies are needed to confirm whether PTX3 and sTWEAK could be useful biomarkers to investigate potential mechanisms underlying the relationship between periodontitis and atherosclerotic vascular diseases." (PMID 31583485, 2020). "Periodontitis, mainly in moderate or severe levels, causes a more extensive systemic inflammatory response, thereby promoting dysfunction in the vascular endothelium, with high serum levels of IL-6, PTX3, sTWEAK, and Aβ1-40 associated with a poor prognosis in patients with lacunar, infarcts." (PMID 40231146, 2025). "In a 2019 study, the levels of PTX3 were found to be significantly higher in patients who had chronic periodontitis at the beginning of the study." (PMID 37240630, 2023). "The low abundance of the pro-inflammatory molecule PTX3, an acute phase protein increased during aggressive periodontitis, or the complement component C9 is in agreement with the histological and clinical findings reported." (PMID 34777248, 2021). "PTX3, which is associated with CKD and periodontitis, is a truly independent indicator of disease activity." (PMID 34211440, 2021). "Serum PTX3 levels were also significantly elevated at baseline in periodontitis + diabetic neuropathy patients, as compared to the other groups." (PMID 34830557, 2021). "The recall evaluation showed that GCF PTX3 levels decreased after NSPT in both periodontitis groups, although the decrease for the P group (−43,75%) was superior to that of the HCV+P group (−39,47%)." (PMID 34830557, 2021). "The authors found that, at baseline, the GCF PTX3 levels were highest in patients with periodontitis, as compared to controls, and that these levels were significantly reduced as soon as two weeks after performing scaling and root planning on these patients." (PMID 34830557, 2021). "Our group has reported higher levels of PTX3 and sTWEAK in patients with CM and concurrent severe periodontitis as well as higher levels of PTX3 and sTWEAK in CM patients." (PMID 32244987, 2020). "Our group demonstrated higher levels of PTX3 and sTWEAK in patients with severe periodontitis and CM." (PMID 32244987, 2020). "Experimental periodontitis posed an acute systemic inflammatory response with increased serum levels of IL-6 and PTX3 at 24 h post-induction, followed by a significant overexpression of sTWEAK at 7 days." (PMID 31583485, 2020).